SUSD2 (sushi domain containing 2)
Diseases named in the same sentence as SUSD2 in open-access papers (continued):
Sharing a sentence is not in itself a finding about the gene and the disease.
tumor (29 papers, 2010 to 2025). "The downregulated genes (DEPTOR, DPEP1, NAT8, and SUSD2) in the tumor and thrombus were associated with a worse survival rate when the gene was less expressed in the tumor, and the same correlation was observed for the upregulated genes (PLOD2 and SLC7A5)." (PMID 37328520, 2023). "Studies have indicated that SUSD2 expression may be associated with both favorable and unfavorable cancer prognoses and that its biological function may be either an oncogene or a tumor suppressor, depending on the cancer type and stage 10-14." (PMID 39247587, 2024). "In conclusion, we show, for the first time, that SUSD2 is expressed in CTCs and appears to affect key proteins in tumor progression and survival." (PMID 39890941, 2025). "If located on the cell surface, galectin-1 can introduce T cell apoptosis, so that SUSD2 contributes to the evasion of tumor cells from targeting by the immune system." (PMID 39890941, 2025). "The knockdown of SUSD2 in SMMC-7721 human HCC cells can increase growth and decrease apoptosis, whereas the overexpression of SUSD2 decreases tumor growth and increases apoptosis in HepG2 human HCC cells." (PMID 39791720, 2024). "As well as a tumor-reversing protein, SUSD2 (encoding sushi domain containing 2) also plays a dual role during neural development." (PMID 37107637, 2023). "We previously already identified Endod1 and Susd2 as tumor suppressor genes and as downstream targets of the NOTCH pathway, which harbors potent tumor suppressive capabilities in the skin and oral cavity." (PMID 36765696, 2023). "Previous studies have shown that SUSD2 can function as a tumor suppressor in a wide range of cancers." (PMID 36619866, 2022). "Several ncRNAs, such as miR-491-3p, miR-613,and SUSD2 have been found to act as tumor suppressor genes in RB, but other ncRNAs, such as circ-E2F3, NEAT1, and TUG1 act as tumor promoter genes." (PMID 36619866, 2022). "Consistent with Experimental Arm 1, Experimental Arm 2 showed that knock-down expression of SUSD2 in a HGSOC OVCAR3 mouse model contributes to increased tumor formation." (PMID 32595828, 2020). "Previous studies using in vitro methods have indicated that SUSD2 functions as a tumor suppressor in several cancers, including HGSOC." (PMID 32595828, 2020). "Altogether, our findings gathered from Experimental Arm 1 showed that knock-down of SUSD2 in OVCAR3 cells contributes to higher overall tumor burden in a HGSOC mouse model." (PMID 32595828, 2020). "IHC analysis was performed using both anti-pan-cytokeratin and anti-SUSD2 antibodies to visualize tumor cells and contrast the level of SUSD2 in tumors from each cohort of mice." (PMID 32595828, 2020). "The SUSD2 expression had a significant correlation with the clinicopathological parameters such as gender, smoking history, differentiation grade, tumor length, T stage, N stage and TNM stage (all P < 0.05)." (PMID 32194777, 2020). "We compared the expression levels of SUSD2 in tumor tissues of different pathological stages and also non-tumor tissues." (PMID 32194777, 2020). "We found SUSD2 mRNA level in the LUAD tumor tissues was significantly lower than that in adjacent normal tissues." (PMID 32194777, 2020). "In a syngeneic mouse model, tumors with Susd2 had increased angiogenesis and decreased T cells in the tumor microenvironment." (PMID 31387209, 2019). "This experiment provides additional evidence that SUSD2 increases the M2 polarized macrophages in the tumor microenvironment." (PMID 28475599, 2017). "Here we show that SUSD2-expressing BCa cells potentiate angiogenesis indirectly by the recruitment of macrophages into the tumor by secretion of MCP-1 and by secreting angiogenic factors that directly stimulate endothelial vessel formation." (PMID 28475599, 2017). "Further, this report showed that accelerated tumour formation and decreased survival rates in mice with tumours expressing SUSD2 were also observed in a syngeneic mouse model." (PMID 28841682, 2017).
tumor (continued). "An in vitro co-culture assay was developed to support the findings in patient tumor sections that SUSD2 skews macrophages towards an M2, pro-tumor phenotype." (PMID 28475599, 2017). "Our data indicates that patient tumors with strong SUSD2 staining had increased CD68 staining of macrophages in the tumor." (PMID 28475599, 2017). "Taken together, the results indicate that SUSD2 functions as a tumor suppressor and play a role in cellular proliferation." (PMID 26933386, 2016). "Taken together, these results suggested that SUSD2 played as a tumor suppressor and thus inhibited the growth of HCC tumors in vitro." (PMID 26933386, 2016). "For SUSD2 IHC staining in HCC tissues and normal liver tissues, SUSD2 is primarily expressed in the cytoplasm within tumor cells." (PMID 26933386, 2016). "The present observation that SUSD2 expression remained unchanged in our hypoxia/re-oxygenation experiments suggests that SUSD2 might be a stable CTC marker reflecting the expression in the tumor tissue(s)." (PMID 39890941, 2025). "In lung cancer and RCC, lower SUSD2 expression also acted as a tumor suppressor." (PMID 36619866, 2022). "The finding that C10orf99 suppresses proliferation in tumor cells via SUSD2 led to the hypothesis that similar effects could be evoked via GPR15 in cancer." (PMID 34639163, 2021). "Apart from GPR15, however, C10orf99 may act as a tumor suppressor by suppressing proliferation of several tumor cell lines via G1 arrest by interacting with another binding receptor, called sushi domain containing 2 (SUSD2)." (PMID 34639163, 2021). "Interestingly, SUSD2 has been shown to prevent senescence and cell death in tumor cells, suggesting its induction is important for expansion of cultured eMSC." (PMID 32984350, 2020). "Because previous in vitro analysis confirmed that SUSD2 inhibits mesothelial clearance in HGSOC cells, we hypothesized that decreased SUSD2 expression in HGSOC cells increases the overall tumor burden and contributes to shorter survival." (PMID 32595828, 2020). "SUSD2 is a plasma membrane protein thought to be a tumor suppressor acting via G1 cell-cycle arrest, but its role in early human development is unknown." (PMID 32302559, 2020). "However, there were also some studies reported that SUSD2 played a tumor oncogene role in tumorigenesis." (PMID 32194777, 2020). "Whether SUSD2 functions as a tumor suppressor in LUAD and how are still worth studying in the future." (PMID 32194777, 2020). "This suggested that SUSD2 may function as a tumor suppressor and prognostic marker in HGSOC patients with late-stage diagnosis." (PMID 32595828, 2020). "SUSD2 interacts with GAL1 to promote tumor immune evasion, angiogenesis, and metastasis." (PMID 31426508, 2019). "High SUSD2 expression significantly associated with differentiation but not with tumor depth, invasive growth, lymph node metastasis, lymphatic involvement, vessel invasion, or tumor stage." (PMID 30259711, 2018). "Using a syngeneic mouse model, we observed accelerated tumor formation, decreased survival of mice and increased angiogenesis in Susd2-expressing tumors, suggesting that SUSD2 may play a role in tumor neovascularization." (PMID 28475599, 2017). "Two previous studies described the mouse homolog SUSD2 as a potential tumour suppressor." (PMID 28841682, 2017). "SUSD2 (Sushi Domain Containing 2) was first identified in mouse as a tumor-reversing gene." (PMID 26933386, 2016). "Our findings suggest that SUSD2 may play as a tumor suppressor in HCC cells and could be served as an additional potential marker for diagnosis." (PMID 26933386, 2016). "The results demonstrated that low expression of SUSD2 was positively correlated with tumor advanced clinical stage (χ2 = 30.244, P < 0.05), pT status (χ2 = 33.175, P < 0.05), pN status (χ2 = 4.785, P < 0.05) and histological grade (χ2 = 5.198, P < 0.05), pM status (χ2 = 4.620, P < 0.05)." (PMID 26933386, 2016).
tumor (continued). "We have proven that up-regulation of SUSD2 may reverse tumor formation, making it a potentially effective biomaker,but the mechanisms of SUSD2 in HCC carcinogenesis and the prognostic value of SUSD2 in HCC patients are needed in further studies." (PMID 26933386, 2016). "Their work indicated a possible tumor suppressive role of mouse SUSD2." (PMID 26933386, 2016). "Hence, both organs might be considered as the originating tissue, which harbored the metastasis where tumor cells changed the SUSD2 regulation towards stable SUSD2 expression under hypoxia." (PMID 39890941, 2025). "In vitro assays and clinically annotated tissue microarrays (TMAs) collectively support the notion that SUSD2 may function as a tumor suppressor in ovarian, renal, lung, liver, and colon cancer, although the exact mechanism of tumor suppression remains to be elucidated." (PMID 32595828, 2020). "Therefore, SUSD2-mediated surface presentation of Gal-1 may be contributing to tumor immune evasion." (PMID 31387209, 2019). "Metastasis is the main cause of cancer recurrence and tumor-related death, the absence of SUSD2 in HCC may represent advanced disease and poor prognosis for the patient." (PMID 26933386, 2016). "In the RM+ group under 2D conditions, tumour suppressor genes, CDKN1A and NR4A3, were upregulated and tumour-promoting genes, CA9, EFNA1, and SUSD2, were downregulated." (PMID 41381717, 2025). "In a general image, it appeared that the originating tumor cells of CTC-ITB-01 were at least temporarily confronted with adverse microenvironmental conditions, which also had an effect on SUSD2." (PMID 39890941, 2025). "For the cancer-extrinsic roles of SUSD2 in the TME, it has been shown that SUSD2 can interact with interleukin-2 receptor (IL-2R) alpha and lead to the impairment of anti-tumor CD8+ T cell function." (PMID 39791720, 2024). "SUSD2 can directly regulate the expression of chemokine (C-C motif) ligand 2 (CCL2), which is responsible for recruiting macrophages to the tumor microenvironment." (PMID 39791720, 2024). "Among these six hub genes, DEPTOR, DPEP1, NAT8, and SUSD2 were expressed at their highest levels in normal tissues, whereas PLOD2 and SLC7A5 were expressed at their highest levels in tumor thrombi." (PMID 37328520, 2023). "In this study, we showed that the expression of SUSD2 is downregulated at both the mRNA and protein levels in LUAD tumor tissues using bioinformatic analysis and IHC." (PMID 32194777, 2020). "We then analyzed the SUSD2 expression level of the LUAD cases from the TCGA database and there was a significant difference between the LUAD tumor tissues and normal tissues." (PMID 32194777, 2020). "Sushi Domain Containing 2 (SUSD2), a transmembrane protein on BCa cells, was previously shown to promote tumor angiogenesis in a murine model." (PMID 28475599, 2017). "Approximately 80% of tumors had moderate to strong SUSD2 staining regardless of subtype or tumor characteristics." (PMID 28475599, 2017).
cancer (25 papers, 2016 to 2025). A tumor composed of atypical neoplastic, often pleomorphic cells that invade other tissues. "CENPM and SUSD2 have roles in cell cycling and proliferation with mutations associated with cancers." (PMID 36952446, 2023). "SUSD2 has been linked to proliferation in cancer cells, why we investigated the proliferation status of the cells with the proliferation marker Ki-67." (PMID 35058936, 2021). "SUSD2 is also expressed in certain cancers, in which it has been linked to proliferation; thus, one could imagine that cells with high SUSD2 expression are proliferating." (PMID 35058936, 2021). "Dysregulated expression of SUSD2 in human cancer can be attributed to various factors, including promoter methylation, genetic variations, dysfunctional oncogenic signaling, and miRNA regulation." (PMID 39247587, 2024). "Understanding the precise mechanisms governing SUSD2 regulation is crucial for developing targeted therapeutic strategies aimed at manipulating its activity and ultimately influencing the course of cancer progression." (PMID 39767561, 2024). "To determine the molecular mechanism underlying the effect of SUSD2 on cancer cell progression, we used bioinformatics to identify miRNAs and discovered that miR-383-5p targeted the 3'UTR of SUSD2." (PMID 39247587, 2024). "They showed that methylation is associated indirectly with metastatic cell behavior—increases cell migration and invasion, and that upregulation of suppression gene SUSD2 (Sushi Domain Containing 2) can reduce cancer cell expansion." (PMID 33809784, 2021). "We analyzed the expression profile of SUSD2 in different types of human cancers using the Oncomine database." (PMID 32194777, 2020). "Several studies have reported the role of SUSD2 in cancer and SUSD2 seemed to sever as a valuable factor for tumorigenesis in different types of cancer 5, 8-11, 14-17." (PMID 32194777, 2020). "Since then, several publications have begun to explore SUSD2 expression in the context of multiple cancers including ovarian, breast, lung, renal, gastric, liver, and colon." (PMID 32595828, 2020). "In general, the result on the role of SUSD2 in cancer remains controversial and it seems that SUSD2 can regulate different signal transduction processes determined by the cell types." (PMID 32194777, 2020). "Oncomine analysis of cancer vs normal samples revealed that SUSD2 expressed statistically significantly higher in LUAD comparing to normal tissues." (PMID 32194777, 2020). "Sushi Domain Containing 2 (SUSD2) has been studied in cancer, neurodevelopment, and as a marker for mesenchymal stem cells." (PMID 31387209, 2019). "Although recent studies have focused on the relationship between SUSD2 expression and multiple types of human cancer, such as breast, colon, the expression pattern of SUSD2 protein and its biologic function has not been revealed in HCC." (PMID 26933386, 2016). "Currently, SUSD2 has been reported to be dysregulated in some cancers and accumulating evidences suggested that reduced expression of SUSD2 plays a key role in tumorigenesis." (PMID 26933386, 2016). "For each patient sample, a trained pathologist scored the percentage of cancer epithelial cells that stained positive for SUSD2 on the HGSOC TMA." (PMID 27775699, 2016). "Previously, various reports have demonstrated the function of SUSD2 in cancer." (PMID 39791720, 2024). "This dual role highlights the intricate relationship between SUSD2 and cancer development." (PMID 39767561, 2024). "SUSD2 plays a complex role in human cancer and exhibits duality influenced by the type of cancer." (PMID 39247587, 2024). "Together, these findings suggest multiple functions of SUSD2 that may depend on the type of cancer and/or microenvironment." (PMID 32595828, 2020). "In cancer, SUSD2 has been described as both protumor and antitumor depending on the type of cancer." (PMID 31387209, 2019).
cancer (continued). "Therefore, we conducted a PCR array analysis to identify cancer‐related genes expressed coordinately with SUSD2 with the aim of acquiring evidence to implicate SUSD2 in cancer progression." (PMID 30259711, 2018). "Since SUSD2 is a membrane protein that is abundant in 80% of patient BCa samples, further study of this pathway may lead to the identification of novel therapeutic targets to inhibit the function of SUSD2 and ultimately impede cancer metastasis." (PMID 28475599, 2017). "Our lab has previously demonstrated that Galectin-1 is only presented on the surface of BCa cells when SUSD2 is present; therefore, SUSD2 presentation of Galectin-1 on the cancer cell membrane may allow direct regulation of macrophage phenotype upon cell contact." (PMID 28475599, 2017). "Up to present, the published work suggests that the status of SUSD2 expression may be an important factor in tumorigenesis, but the function in different cancers may be different; furthermore, little is known about the effect of SUSD2 expression on HCC patients and prognosis." (PMID 26933386, 2016). "Furthermore,in our study, we proved that up-regulation of SUSD2 significantly decreased the migration and ability of HepG2 cells to invade through Matrigel, a basement membrane that used to imitate the metastatic potential of cancer cells." (PMID 26933386, 2016). "OVCAR3-NT mice developed significantly less cancer cell infiltrate and tumors in their pancreas and omentum compared to OVCAR3 SUSD2-KD mice." (PMID 32595828, 2020). "GPR15L is also a high affinity ligand for SUSD2, and co-expression of SUSD2 and GPR15L inhibits growth of some cancer cell lines by inducing G1 arrest." (PMID 28936214, 2017). "A 2-fold increase in polarized M2 macrophages was observed when M0 macrophages were incubated with SUSD2-expressing BCa cells compared to cancer cells that do not contain SUSD2." (PMID 28475599, 2017). "Oxaliplatin uniquely upregulated SUSD2, which is commonly downregulated in CRC and interacts with the potential novel cytokine CSBF/C10orf99 to inhibit CRC cell growth, and SAT1, whose levels are also lower in patients with cancer and plays a critical role in ferroptosis." (PMID 34611476, 2021). "Future studies investigating how SUSD2 expression in HGSOC may impact other factors that affect patient outcome, such as chemotherapy resistance of spheroids or the ability of the cancer cells to evade the immune system, will increase our understanding of the dynamic phenotypes of SUSD2 in cancer." (PMID 32595828, 2020).
infection (1 paper, 2025). The state of being infected such as from the introduction of a foreign agent such as serum, vaccine, antigenic substance or organism. "Additionally, genes related to cell adhesion such as ADGRF5, CAVIN2, FAT3, FILIP1, GSN, and TSPAN11 were downregulated in both the variants at 24hpi whereas CAV1, CAVIN1, GPC3, POSTN, SUSD2, and TSPAN7 were downregulated only after Delta variant infection at 24 hpi." (PMID 41200555, 2025).
kidney disease (1 paper, 2025). "It should be noted that SUSD2 dysregulation is not entirely specific to kidney disease—abnormal levels have been identified in malignancies as well." (PMID 40004202, 2025).
SUSD2 also shares sentences with these, for which no sentence is quoted: renal cell carcinoma (4 papers); breast invasive carcinoma (1); cervical carcinoma (1); cholangiocarcinoma (1); colon adenocarcinoma (1); colorectal cancer (1); dysgerminoma (1); endometrial disorder (1); esophageal cancer (1); fibrosarcoma (1); head and neck squamous cell carcinoma (1); kidney chromophobe (1); liver cancer (1); lung squamous cell carcinoma (1); major depression (1); non-small cell lung carcinoma (1); ovarian adenocarcinoma (1); pancreatic cancer (1); psychosis (1); rectum adenocarcinoma (1); sarcoma (1); thyroid carcinoma (1); triple-negative breast carcinoma (1); urothelial carcinoma (1).